RUNX2 (RUNX family transcription factor 2)
Diseases named in the same sentence as RUNX2 in open-access papers (continued):
Sharing a sentence is not in itself a finding about the gene and the disease.
hematological malignancies (3 papers, 2017 to 2023). "All MYC+RUNX2-DKO mice died 1 month post-transplantation, whereas there were no lethal hematological malignancies in MYC+RUNX2-WT or DKO mice 6 months post-transplantation." (PMID 30971697, 2019).
inflammation (2 papers, 2022 to 2025). Aberrant reaction of the microcirculation characterized by movement of fluid and leukocytes from the blood into extravascular tissues. "Runx2 have a direct correlation with persistent periapical inflammation and bone regeneration after endodontic treatment." (PMID 39687469, 2025).
metabolic disease (2 papers, 2024 to 2025). A congenital disorder (due to inherited enzyme abnormality) or acquired (due to failure of a metabolically important organ) disorder resulting from an abnormal metabolic process. "One study confirmed an opposing relationship between adipogenesis and osteogenesis via the identification of the mechanism of deacetylation of RUNX2 by Sirt-1, which is known as a major regulator of longevity and metabolic disorder." (PMID 38927789, 2024). "In the clinical setting, specifically in ageing and metabolic diseases where one of the hallmarks is vascular mineralization, RUNX2 could be a valuable therapeutic target." (PMID 41511334, 2025).
musculoskeletal disorders (2 papers, 2022 to 2025). "While BMPR2 is a well-known target of miR-125b in musculoskeletal disorders, RUNX2 is always described as an indirect target." (PMID 39897583, 2025).
blood cancers (1 paper, 2025). "Notably, specific genes like RUNX Family Transcription Factor 1 (RUNX1) and RUNX Family Transcription Factor 2 (RUNX2), have been demonstrated to play significant roles in both normal hematopoiesis and the development of blood cancers." (PMID 40426895, 2025).
GI tumors (1 paper, 2021). "In our study, higher RUNX2 expression was detected in GII tumors compared to GI tumors, whereas NKX2-1 seemed to be specifically expressed in GI tumors." (PMID 34001209, 2021).
infectious disease (1 paper, 2023). A disorder directly resulting from the presence and activity of a microbial, viral, or parasitic agent in humans. "The six pathway groups are “Metabolism”, “Regulation of expression of SLITs and ROBOs”, “Infectious disease”, “Nonsense-Mediated Decay (NMD)," “Translation”, and “Transcriptional regulation by RUNX2”." (PMID 37759792, 2023).
mental disorders (1 paper, 2022). A disease that has its basis in the disruption of mental process. "Therefore, RUNX2, whose expression plays an important role in the brain development (thalamus, hypothalamus and hippocampus) is considered a candidate gene for serious mental illnesses, such as schizophrenia and bipolarity." (PMID 36611845, 2022).
myopathy (1 paper, 2017). A disease of the muscle in which the muscle fibers do not function properly. "Our findings extended the phenotypic spectrum of the RUNX2 p.R225Q mutation, from typical dental/skeletal abnormalities to a limb-girdle pattern of myopathy." (PMID 28056872, 2017). "Therefore, we hypothesized that mutations in the RUNX2 gene may lead to damaging effects in muscle cell maturation, which result in myopathy." (PMID 28056872, 2017). "Those carriers of the RUNX2 p.R225Q mutation reported no neurological complaints; in particular, there were no symptoms or signs of myopathy." (PMID 28056872, 2017).
vasculopathies (1 paper, 2014). "For the induction of an osteochondrogenic phenotype, the contribution of TGFβ signalling, BMPs-SMADs-RUNX2 signalling, Wnt-MSX2 signalling, apoptosis, oxidative stress and ER stress are well appreciated in calcified vasculopathies." (PMID 24775865, 2014).
RUNX2 also shares sentences with these, for which no sentence is quoted: multiple myeloma (13 papers); ankylosing spondylitis (7); heart failure (4); Hypercalcemia (4); rheumatoid arthritis (4); developmental delay (3); idiopathic pulmonary fibrosis (3); scoliosis (3); achondroplasia (2); Alzheimer disease (2); aortic aneurysm (2); arteriosclerosis (2); B-cell lymphoma (2); bone fracture (2); cognitive deficits (2); colorectal adenocarcinoma (2); COVID-19 (2); end-stage renal disease (2); endometrial cancer (2); gout (2); myeloid leukemia (2); osteitis (2); Osteoblastoma (2); secondary hyperparathyroidism (2); type 1 diabetes mellitus (2); Ureteral obstruction (2); acute erythroleukemia (1); acute promyelocytic leukemia (1); adenomyosis (1); allergic asthma (1).
A further 117 diseases each share a sentence with RUNX2 in 1 paper.